CCND1 (cyclin D1)
Diseases named in the same sentence as CCND1 in open-access papers (continued):
Sharing a sentence is not in itself a finding about the gene and the disease.
tumor (continued). "NGS performed on a tumor sample from the liver biopsy obtained at the time of diagnosis revealed CDKN2A mutation A102P, ARID1A mutation I1485fs*5, CCND1 amplification, FGF19 amplification, FGF3 amplification and FGF4 amplification." (PMID 24931142, 2014). "The expression of p21, cyclin D1, and cleaved caspase-3 was also detected in xenograft tumor tissues by immunohistochemical (IHC) staining." (PMID 25422887, 2014). "In particular, we examined risk of CRC according to tumour site, TNM-stage, expression of beta-catenin-, p 53 and cyclin D1, and microsatellite instability (MSI) screening status." (PMID 24885829, 2014). "Their loss, by releasing the inhibition upon tumor-promoting genes, such as BCL2, BMI1, CCND2 and CCND1, promotes cell growth and tumor progression." (PMID 24566314, 2014). "Regarding the clinicopathological factors, most of the studies reported prognostic factors of cyclin D1 expression referring to tumor size, nodal metastasis, histological grade and clinical stage." (PMID 24675814, 2014). "The cell proliferating related cyclin D1 expressions were found to be higher in A549 control tumor lysates." (PMID 24614362, 2014). "In humans, DACH1 is known to repress tumorigenesis in human breast and prostate cancers and down regulates EGFR and cyclin D1 in tumour cells." (PMID 24392136, 2014). "Mechanistically we demonstrate that the activity of KPT-185 is associated with nuclear retention of Fbw7; which degrades nuclear Notch-1 leading to decreased tumor promoting markers such as C-Myc, Cyclin-D1, Hes1 and VEGF." (PMID 24899509, 2014). "60–80% of the tumors cells showed strong Ki-67 staining and Cyclin D1 positivity, demonstrating that the tumor cells were actively proliferating." (PMID 25162504, 2014). "We recently found evidence that STAT1 in esophageal squamous carcinoma (ESCC) cells exerts tumor suppressor function, and it regulates five key regulators of apoptosis or cell-cycle progression, including Bcl-2, Bcl-xL, survivin, cyclin D1 and p21." (PMID 25438156, 2014). "Much attention has been focused on the involvement of cyclin D1 in tumor development and progression." (PMID 24728073, 2014). "curcumin has been shown to suppress the expression of a variety of NF-κB regulated gene products involved in carcinogenesis and tumor growth including cyclin D1, VEGF, COX-2, c-myc, Bcl-2, ICAM-1 and MMP-9." (PMID 25866478, 2014). "In consecutive sections of an HCC, PRO2000/ANCCA, Ki-67 and cyclin D1 were showed to be co-expressed in the same cancer cell within individual tumor." (PMID 24708861, 2014). "Mel-Juso cells overexpressing miR-125b were tumourigenic in mice, but the tumours exhibited higher level of cell senescence and decreased expression of proliferation markers, cyclin D1 and Ki67 than the control tumours." (PMID 24762088, 2014). "Ccnd1, a member of the cyclin family, which is involved in cell-cycle G1/S transition and interactions with tumor suppressors, is overexpressed." (PMID 25566190, 2014). "The LATS2 expression was increased in the control cell tumors compared with that observed in the MIR31-expressing tumor cells, and the CCND1 levels were increased in the tumors formed from MIR31-expressing cells." (PMID 24779718, 2014). "The Wnt/β-catenin signaling pathway has been shown to play an important role in the regulation of cyclin D1, which is crucial in cell cycle regulation and progression in a variety of tumor cells." (PMID 24765191, 2014). "Cyclin D1 activity is critical for tumor formation induced by other oncogenes (e.g. Ras), as mice deficient in cyclin D1 are resistant to tumorigenesis." (PMID 25437003, 2014). "Expression of Bmi1 is influenced by ERα, and the activity of the ERα-coupled Bmi1 signature impacts p16INK4a and cyclin D1 status and thus correlates with the tumor molecular subtype and biologic behavior." (PMID 24559156, 2014). "The activation of this pathway is known to increase cyclin D1 expression in tumor-derived cell lines." (PMID 24504050, 2014).
tumor (continued). "CAPE and CAPPE further significantly inhibited the expression of FASN, cyclin D1, cyclin E, Cdk4 and c-myc proteins of tumor tissues in an in vivo animal study." (PMID 24960186, 2014). "It has been reported that cyclin D1 plays an important role in tumor development through regulation of the cell cycle." (PMID 25341494, 2014). "As expected, we confirmed in individual tumor samples of our patients an inverse correlation of these target mRNA and miR-107 expression levels, being this correlation significant for CCND1, DICER1, DROSHA and NFKB1." (PMID 25197016, 2014). "Next, we investigated the effect of RocA on cell proliferation in vivo by hematoxylin and eosin (H&E) staining and examining Ki-67 and cyclin D1 expression in tumor tissues harvested from vehicle- and RocA-treated mice." (PMID 24568222, 2014). "In summary, for the first time, we discovered the CagA-PI3K/AKT-Sp1-RBP2-Cyclin D1 pathway that contributed to the switch from chronic inflammation to tumor in GC development." (PMID 25015565, 2014). "In xenograft tumor models, the inhibited tumorigenesis in cells with Pin1 knockdown was partially recovered by cyclin D1 restoration." (PMID 25160749, 2014). "We found that MIF and cyclin D1 were overexpressed in 71% (66/93) and 41% (38/93) of tumor samples, respectively." (PMID 25015194, 2014). "From the results we got, we find the novel CagA-PI3K/AKT-Sp1-RBP2-Cyclin D1 pathway that links chronic inflammation to tumor during GC development." (PMID 25015565, 2014). "Histological analysis of the residual tumor remaining after exposure to oral Gltn demonstrated markedly reduced CcnD1 expression and elevated phosphorylation of Chk2." (PMID 24658335, 2014). "We evaluated the expression of MIF and cyclin D1 by performing immunohistochemistry on 93 tumor specimens from HCC patients." (PMID 25015194, 2014). "We used IHC staining to determine the expression of ER-α, PR, HER-2/neu and to identify intrinsic subtypes using formalin-fixed, paraffin-embedded tumor blocks, western blot analysis of c-Myc, cyclin D1 and VEGF gene expression." (PMID 25230850, 2014). "In agreement with the high tumor growth rate, the proliferation markers cyclin D1 and Ki67 indicated that these tumors were highly proliferative." (PMID 25329316, 2014). "Celecoxib has been shown to inhibit cancer growth independently of COX-2 expression levels with a G0/G1 cell cycle arrest and decreased levels of CCNA and CCNB1 or CCND1 depending on tumor type." (PMID 24605326, 2014). "NAD(P)H dehydrogenase, quinone 1 (NQO1) mRNA levels increased in peripheral blood mononuclear cells, and NF-κB and cyclin D1 levels decreased in tumor biopsies." (PMID 24552536, 2014). "Conclusively, these findings indicate that WT1 promotes growth of tumor in vivo and also depends upon up-regulation of the expression of Cyclin D1 and p-pRb." (PMID 23936312, 2013). "Targeted disruption of Nemo-like kinase inhibits tumor cell growth by simultaneous suppression of cyclin D1 and cyclin-directed kinases in human HCC." (PMID 23951254, 2013). "Immunohistochemical (PCNA) and RT-PCR (Cyclin D1) analysis revealed over expression of PCNA and cyclin D1 in the buccal mucosa of hamsters treated with DMBA alone (tumor bearing hamsters)." (PMID 28239123, 2013). "Log-rank one-way method and multi-factor Cox proportional hazards regression models for tumor classification identified cyclin D1 as the independent factor affecting patient survival time." (PMID 24223635, 2013). "Immunohistochemical analysis of tumor tissue for molecular targets of cell cycle such as CCND1, CCNE1, pRB and PCNA demonstrated a significant decrease in expression level accompanied by a moderate decrease in KI67 in response to P276-00 treatment." (PMID 23414419, 2013).
tumor (continued). "Cyclin D1 is also intimately involved in resistance to apoptosis, making it an attractive therapeutic target for controlling tumor growth." (PMID 23555719, 2013). "Overexpression of cyclin D1 mRNA and protein has been observed in several types of solid tumors, including HCC, and is associated with the early onset of cancer and aggressive tumor progression." (PMID 23555719, 2013). "The p16INK4a transgene dramatically delayed mammary tumorigenesis by ErbB2, indicating that ErbB2-mediated deregulation of cyclin D1/Cdk4/6 is a crucial step of tumor formation." (PMID 24205004, 2013). "The activation of cyclin D1 participates in tumorigenesis, local tumor recurrence, and poor prognosis of NPC." (PMID 24222746, 2013). "High waist circumference was associated with beta-catenin positive (ptrend =0.009), cyclin D1 positive (ptrend =0.009), p 53 positive (ptrend =0.003), and MSS (ptrend =0.012) tumours." (PMID 24256736, 2013). "This showed that the tumor grading and cyclin D1 were independent factors affecting laryngeal SCC patient survival by the Cox regression model of risk factors proportion analysis." (PMID 24223635, 2013). "The transcriptomic analysis revealed marked downregulation of the RB tumor suppressor pathway with major players such as cyclin D1, CDK4, and E2F mRNAs strongly suppressed." (PMID 23902736, 2013). "Unexpectedly, analysis of the data indicated that key effectors of the cell cycle like cyclin D1, cyclin E1, growth arrest and DNA damage, and cullin 1, were the primary targets of the transcriptional modifications imposed on these tumor cells." (PMID 23646174, 2013). "p16, Cyclin D1 and CDK4 are cell cycle regulatory factors, and their gene mutations or protein abnormalities are closely related to tumorigenesis, tumor development and progression in a variety of tumors." (PMID 23842094, 2013). "A chemotherapy agent such as BA that can specifically degrade AR and cyclin D1 is especially important in PC therapy due to the importance of these proteins in tumor progression." (PMID 23424652, 2013). "The expression of a large number of genes related to tumor progression, including those for cyclin D1, c-myc, vascular endothelial growth factor, and survivin is controlled via the Wnt/β-catenin pathway." (PMID 24204729, 2013). "In comparison to the control group, the staining intensities of HER2 and cyclin D1 were dramatically downregulated in GTE-treated tumor cells (200 mg/kg/day)." (PMID 23662119, 2013). "EIF4E is a key factor in cap-dependent translation initiation (including several important oncoproteins such as c-Myc, cyclin D1, hypoxia-inducible factor 1, and Mcl-1) that controls tumor cell growth and survival." (PMID 23383345, 2013). "Statistically significant correlations emerged between cyclin D1 and a lower tumor grade (P = 0.013), ER and PR positivity (P = 0.000, P = 0.024, respectively) and a negative or low proliferation rate (P = 0.031)." (PMID 23336272, 2013). "KLF8 knockdown in the cancer cells resulted in reduced xenografted tumor growth in nude mice with decreased expression of cyclin D1 and Bcl-2, the upregulation of pro-apoptotic gene expression and apoptosis in the tumor cells." (PMID 23722127, 2013). "PIN1 is also involved in increasing tumor cell growth and colony formation through the upregulation of the expression of β-catenin and cyclin D1 in several types of cancer." (PMID 24179535, 2013).
tumor (continued). "NF-κB plays significant roles in tumor proliferation and experimental studies verified that NF-κB binding to the cyclin D1 promoter is important for the cyclin D1 regulation." (PMID 23579957, 2013). "This facilitates the transcription of various target genes, e.g. cyclin D1, hence contributing to tumour progression." (PMID 23337059, 2013). "The p16 protein exerts a tumor suppressor function by binding to the cyclin D1 CDK4/CDK6 complex, preventing the phosphorylation of the retinoblastoma (Rb) protein and resulting in G1 arrest." (PMID 24319475, 2013). "Silencing p21 and cyclin D1 expression using siRNAs significantly reduced the rate of primary tumor formation and tumor size." (PMID 23786849, 2013). "The expression of ER-α36 and c-src/p-c-Src and cyclin D1 was examined by western blot analysis, and tumor cell growth was analyzed by cell proliferation and nude mouse xenograft assays." (PMID 24137325, 2013). "We know that high β-catenin/TCF activity is able to drive cell proliferation during tumor formation by turning on the cell-cycle regulator Cyclin D1, and c-Myc serves as important role in prognosis of NB." (PMID 24308762, 2013). "This is in agreement with previous studies showing that depletion of cyclin D1 prevented tumor development in oncogenic HER2 overexpressing transgenic mice." (PMID 23786849, 2013). "MiR-155 also targeted casein kinase 1α (CK1α), which enhanced β-catenin signaling and cyclin D1 expression, thereby promoting tumor cell growth." (PMID 24073882, 2013). "In liposarcoma, miR-155 targets CK1-α to enhance Beta-catenin signaling and cyclin D1 expression and promote tumor cell growth." (PMID 24073882, 2013). "Constitutive accumulation of cyclin D1 in the nucleus has been shown to promote tumor transformation." (PMID 23786849, 2013). "Remarkably, in lymph nodes of 62% of MCL patients in our series (13/21 cases) both CK2α and CK2β were strongly expressed in tumor cells as compared to normal residual areas and their expression overlapped the expression pattern of Cyclin D1 (panels D-E-F)." (PMID 24086494, 2013). "EF24 enhanced the expression of the miR-21 target PTEN in DU145 tumor tissue, but suppressed the expression of markers of proliferating cells (cyclin D1 and Ki67)." (PMID 23940701, 2013). "Cyclin D1 staining in tumor-free as well as tumor-bearing areas was higher after 56Fe radiation relative to control and γ radiation." (PMID 23555653, 2013). "Through increased Wnt signalling, other oncogenic factor such as c-myc and cyclin D1 are activated and drive cells toward a tumour phenotype." (PMID 24194897, 2013). "To further verify the periplocin-inhibited tumor growth in vivo, we also examined the expression of cyclin-D1 in Huh-7 tumors." (PMID 23365613, 2013). "In particular, cyclin D1 and p21 are often over-expressed in human cancers, correlating with high tumor grade, poor prognosis and increased metastasis." (PMID 23786849, 2013). "The researchers also determined that miR-155 targeted casein kinase 1-α (CK1-α), enhancing Beta-catenin signaling and cyclin D1 expression, thereby promoting tumor cell growth." (PMID 24073882, 2013). "Taken together, we found that overexpression of βKlotho suppressed tumor formation by regulating Akt/GSK-3β/cyclin D1 signaling pathway." (PMID 23383245, 2013). "Mutated cyclin D1 with constitutive nuclear localization and impaired degradation not only enhanced cyclin D1 transformation efficiency in vitro, but also promoted tumor formation in vivo." (PMID 23786849, 2013). "The significance of cyclin D1 in tumor growth and metastasis of NSCLC cells has been shown by the use of cyclin D1-targeted siRNA." (PMID 23607551, 2013). "In our results, Cyclin D1 was almost exclusively expressed in the tumor cells stained by CK 8/18, which is a marker of luminal cells in normal breast during development into the final luminal format." (PMID 23327593, 2013).
tumor (continued). "It has also been observed that tumor cells have deregulated CDK or CCND1 activity or combination of both." (PMID 23414419, 2013). "The co-expression of cyclin D1 and p21 proteins are required for the initial steps of tumor development, as double knockdown of these two molecules prevented primary tumor formation in a Xenograft mouse model." (PMID 23786849, 2013). "It has been suggested that cyclin D1 plays a role in the late phase of tumour progression given its correlation with lymph node metastases, histological aggressiveness and poor prognosis." (PMID 23672832, 2013). "Earlier transcriptional profiling studies have shown that cyclin D1 is a critical downstream effector of EGFR signaling and EGF-stimulated cyclin D1 expression is closely associated with tumor development caused by enhanced cell survival and proliferation." (PMID 24340049, 2013). "We found that the suppression of VEGF or CCND1 impaired tumor growth, suggesting that they are tumor-promoting genes." (PMID 24260413, 2013). "In men, significant associations were seen between high BMI, WHR, waist and hip circumference and cyclin D1 positive tumours." (PMID 24256736, 2013). "Among the 134 positive cases, 71 (47.3%) cases exhibited positive staining (5%<cyclin D1<50%) and 63 (42%) were highly positive (>50% of the tumor cells)." (PMID 23420289, 2013). "Chk2 and cyclin D1, hallmarks of tumor proliferation, were also downregulated after PHGDH knockdown." (PMID 23229761, 2013). "The expression level of SATB1 showed correlation with tumor differentiation and pTNM stage, and SATB1 was also associated with the expression of various biologic markers (including Cyclin D1, MMP-2, NF-κB, PCNA, APC and BRAFV600E)." (PMID 23326301, 2013). "It has been demonstrated that NPC are able to migrate towards and infiltrate the primary glioma tumor site and also track along the invasive tumor cells and induce tumor cell death by releasing endogenous anti-tumor signals such as Cyclin D1 and D2." (PMID 24213470, 2012). "HSE directly shows its ability to control various cellular processes such as cell cycle by inhibiting the expression of Cyclin D1, tumor growth and metastasis by down-regulating the Jak2/STAT pathways." (PMID 22792362, 2012). "Metformin markedly reduced the expression of cyclin D1 and increased the number of apoptotic tumor cells compared to the untreated controls." (PMID 23151022, 2012). "More importantly, amplification of CCND1 was the only single gene which correlated with poor survival and had additional prognostic value aside from tumor size, mitotic count, and histological grade using a Cox regression analysis." (PMID 22527098, 2012). "The effects of ACA also correlated with a down-regulation of NF-κB regulated gene (FasL and Bim), including proinflammatory (NF-κB and COX-2) and proliferative (cyclin D1) biomarkers in tumor tissue." (PMID 23043547, 2012). "The CCND1 amplification status was positively correlated to tumour grade (P < 0.001) and proliferation (defined as Ki67 expression) (P < 0.001), but not to nodal status or tumour size." (PMID 22475046, 2012). "In this study, our results from RT-PCR clearly demonstrated that the down-regulation of p-STAT3 was accompanied by the decreased expression of cyclin D1 and Bcl-xL in tumor tissue following M-HIFU treatment." (PMID 22911830, 2012). "We found that treatment with CP-P was effective in down regulating the expression of cyclin D1 and Bcl-2 in tumor tissues." (PMID 23284617, 2012).